CRP (C-reactive protein)
Diseases named in the same sentence as CRP in open-access papers (continued):
Sharing a sentence is not in itself a finding about the gene and the disease.
COVID-19 (continued). "Three patients who lacked blood cell counts or CRP results, 10 who were unable to complete COVID-19 genotyping due to the length of hospital stay less than 24 h or lack of pulmonary CT examination were excluded." (PMID 37089472, 2023). "Anemic COVID-19 patients show the presence of high inflammatory markers like IL6 and CRP." (PMID 35849261, 2023). "Regardless of sex and prior AHT (columns 1, 4, 5), all COVID-19 patients showed an increase in CRP, decreases in alanine, glutamine, lysine, pyruvate, and in the lipoprotein subgroups H4A1, H4CH, and H4PL." (PMID 37845506, 2023). "CRP level was significantly higher in MetS cases with COVID-19 in relation to MetS cases without COVID-19 infection." (PMID 37142990, 2023). "CRP and LDH were significantly increased in PE patients with COVID-19." (PMID 36810085, 2023). "In our cohort of acutely ill patients with moderate to severe COVID-19 ARDS, the marked increase in serum catecholamine levels (particularly norepinephrine) correlated with the degree of systemic inflammation, expressed by CRP and IL-6." (PMID 36836097, 2023). "The inflammatory state, represented by CRP levels and being a major trigger of mood swings in AIT, could be subject to fluctuations by means of an external stimulus such as COVID-19 vaccine antigens." (PMID 37090700, 2023). "and Enterococcus spp., and CRP levels and LoS in COVID-19 patients without and with T2D, while the abundance of other genera, such as Bifidobacterium spp." (PMID 36844398, 2023). "Laboratory parameters CRP, ferritin, ESR, LDH and D dimer are essential to estimate the severity of COVID-19.Laboratory evidence with these abnormal laboratory parameters has been associated with critical and fatal illnesses and in response to T cell immunotherapy tocytokine storm and sepsis." (PMID 37928498, 2023). "This study showed that the most common alterations were increased values of CRP, ferritin, D-dimer, reduced amount of CO2 in serum, and reduced lymphocyte count, and these could be considered as significant biomarkers for COVID-19 prognosis." (PMID 38130539, 2023). "The negative evolution of COVID-19 can be presumed by measuring the IL-6, CRP, lymphocytes, and NLR, which are strongly correlated." (PMID 36838284, 2023). "Research has indicated that COVID-19 patients who were diagnosed with RT-PCR exhibited elevated levels of neutrophil (NEU) count, C-reactive protein (CRP), aspartate aminotransferase, alanine aminotransferase (ALT), lactate dehydrogenase, urea levels in serum, fibrinogen, and hs-CRP levels." (PMID 37443616, 2023). "The main determinants of the severe COVID-19 process in pregnancy are decreased levels of lymphocytes and erythrocytes, electrolyte imbalance, and an increase in alanine aminotransferase (ALT) and C-reactive protein (CRP) levels." (PMID 37546030, 2023). "CRP and SERPINA3, which are considerably more concentrated in the plasma of SEVEREs, have already been pointed out as candidate predictors for worse outcomes in COVID-19." (PMID 36834989, 2023). "Besides many other biochemical parameters, such as CRP, PGRN was a better biomarker for the COVID-19 prognosis." (PMID 37408184, 2023). "Our data also identified CRP, among all investigated analytes, to best discriminate between severe and non-severe forms of disease, while LDH, sTREM-1 and HGF proved to be excellent mortality predictors in COVID-19 patients." (PMID 37388734, 2023). "The median BV score in the viral (non-COVID-19) group was 9 (IQR 0–25.5), whereas the median levels for the individual biomarkers were as follows: TRAIL 110 pg/mL (IQR 79.5–245.5), IP-10 504 pg/mL (IQR 316.5–813), and CRP 12.3 mg/L (IQR 3.7–26.9)." (PMID 36757525, 2023). "The increase in the severity of COVID-19 showed elevated levels of WBC count, neutrophil%, platelet count, neutrophil/lymphocyte ratio, serum ferritin, D-dimer, C-reactive protein, procalcitonin, interleukin-6, and lactate dehydrogenase, and decreased lymphocyte and monocyte percentages." (PMID 37016651, 2023).
COVID-19 (continued). "Regression analysis conducted for age, gender, C-reactive protein (CRP) (inflammatory marker), and iron-related markers in the context of the requirement for hospitalization of COVID-19 patients revealed that only serum iron and ferritin were significantly associated with hospitalization." (PMID 35849261, 2023). "In our study, patients in the severe COVID-19 group had significantly higher CRP levels in contrast to the non-severe COVID-19 group." (PMID 37173883, 2023). "Additionally, receiver operator characteristic (ROC) curves demonstrated that PTX3 had higher accuracy than CRP, lactate dehydrogenase (LD), or ferritin in identifying ICU necessity during COVID-19." (PMID 37408184, 2023). "In non-COVID-19 patients with sepsis, using steroids and Tocilizumab seems to induce a reduction in CRP and PCT levels and less response to infections, which is more pronounced on CRP levels." (PMID 37887237, 2023). "In the mentioned study, it has been demonstrated that patients with severe COVID-19 symptoms displayed higher hs-CRP levels and ferritin levels compared to those lacking symptoms." (PMID 37832397, 2023). "In laboratory findings in COVID-19 patients, the number of lymphocytes and percentage of oxygen saturation decreased, but the levels of liver enzymes (AST and ALT), inflammatory markers (CRP and ESR), and lactate dehydrogenase increased." (PMID 38049886, 2023). "An additional finding of the ROC data shows that the NPV scores support the hypothesis that early normal-range blood parameters (i.e., CK-MB, TnT, FBG, AST, ALT, CK, CRP, albumin, and INR) in Omicron COVID-19 individuals might provide mild or light effects." (PMID 37110348, 2023). "In the present investigation, CRP was higher in COVID-19 patients compared to the COVID-19 negative group." (PMID 36819137, 2023). "Interestingly, our study explored that suPAR has a better prognostic value (AUC = 0.821) than eGFR (AUC = 0.642), CRP (AUC = 0.591), PLT (AUC = 0.560), and LDH (AUC = 0.500), distinguishing COVID-19 patients who will have poor outcomes due to COVID-19." (PMID 37108340, 2023). "C-reactive protein and D-dimer are significantly increased in people with severe disease, there is also a slight increase in aPTT and a decrease in PTI and PV in patients with severe COVID-19." (PMID 37390087, 2023). "Compared with mild COVID-19 patients, severe patients showed raised values of NLR (OR 1.21, P <0.001), PLR (OR 1.01, P <0.001), LMR (OR 0.63, P <0.001), CLR (OR 1.01, P <0.001), PCT (OR 1.09, P =0.01) and CRP (OR 1.02, P <0.001)." (PMID 37860066, 2023). "CRP levels were significantly increased in severe cases compared to mild (one-way ANOVA, Tukey's multiple comparison test, p=0.0002) and moderate (p=0.0036) cases in all three outbreaks of COVID-19." (PMID 36818555, 2023). "Furthermore, ROC analysis revealed that the AUC of the PAR was statistically greater than that of the procalcitonin, WBC, NLR and CRP, indicating that the PAR was superior to these markers in detecting COVID-19 patients requiring ICU support." (PMID 36950410, 2023). "This suggests that CRP increases during hospitalization and ICU admission of COVID-19 patients." (PMID 37228441, 2023). "In addition, the usefulness of CRP and PCT in diagnosing secondary BSI infections in the course of COVID-19 was assessed." (PMID 37762882, 2023). "D-dimer, CRP, IL-6, LDH, and procalcitonin levels increased from mild to severe COVID-19." (PMID 37016651, 2023). "The observed correlation between CRP and megakaryocytes, along with the potential interaction with SPARC, suggests that megakaryocytes could play a role in the immune response to COVID-19." (PMID 38077346, 2023). "The blood-based CRP value was also higher in severely ill COVID-19 patients (mean CRP 180.45 mg/L; SD 81.27) and non-severe patients (mean CRP 111.04 mg/L; SD 79.96, p-value = 0.004)." (PMID 37173883, 2023).
COVID-19 (continued). "Increases in D-dimer, a protein fragment produced during dissolution of blood clots, together with the pro-inflammatory marker, C-reactive protein (CRP), ferritin, TNF-α, IL-1β, IL-6, and IL-13, as well as sPLA2-IIA activity, were also found in patients with COVID-19 compared to normal persons." (PMID 37189799, 2023). "IL-6, CRP, ferritin, LDH, and D-dimer were increased in all COVID-19 forms." (PMID 37239895, 2023). "Parameters taken for analysis in accordance with previous studies and observations in the COVID-19 literature (Block 1) determined the model (p < 0.001) indicating three significant variables: vaccination (yes/not), D-dimer, CRP levels (p < 0.05)." (PMID 37608339, 2023). "It has been previously investigated that CRP can induce TNF-α and IL-23 production by monocytes, so the elevation of TNF-α and IL-23 in COVID-19 patients might be related to CRP-induced monocytes." (PMID 37283736, 2023). "While CRP was used as one of the criteria for determining the severity of infection, the NLR levels were also statistically significantly different between the medium–severe and severe COVID-19 patients." (PMID 36975366, 2023). "We found no sex-related differences in inflammation markers in COVID-19 affected residents during the first two outbreaks, but neutrophil counts, NLRs and CRP levels were significantly higher and lymphocytes lower in males in the third outbreak of our study." (PMID 36818555, 2023). "Other conventional biomarkers, such as CRP, have limited significance and specific cut-off values are lacking so far to discriminate reliably between severe COVID-19 and actual VTE or ATE." (PMID 37231476, 2023). "Cytokine concentrations and CRP were higher in COVID-19 patients (76; ICU & non-ICU) vs. healthy controls (n = 24), all p<0.0001." (PMID 35500008, 2022). "The only sera biomarkers that were increased in patients with COVID-19 in the registry that had a history of CVD compared to those without a CVD history were peak CRP (p = 7.98 × 10−5) and kappa Ig FLCs (p = 0.0032)." (PMID 36292038, 2022). "Neurological symptoms were present in 20% of the COVID-19 pediatric patients, having higher CRP than patients with non-neurological presentations." (PMID 36420294, 2022). "In contrast, our study reported substantially low CRP levels in the pregnant population as compared to non-pregnant COVID-19 infected subjects." (PMID 35371473, 2022). "Some genes that may be related to severe COVID-19 pathophysiology and are good candidates for experimental investigation include PRKG1, ACE, CFB, CRP, CTNNB1, EGFR, and VEGFA." (PMID 35794133, 2022). "The increase in the number of C-reactive protein, PCT, erythrocyte sedimentation rate, ferritin, troponin, D-dimer, lactate dehydrogenase, neutrophils can be a guide in determining the severity of coronavirus disease 2019 (COVID-19)." (PMID 35950826, 2022). "Acute phase reactants, including ferritin and LDH, but not CRP, were higher in patients with COVID-19." (PMID 36422055, 2022). "A positive correlation was observed between the SOFA score as marker for disease severity and CRP, leukocytes, and markers of platelet hyperreactivity in patients with COVID-19 only but not in those with acute respiratory disease of other reason." (PMID 35359931, 2022). "The level of CRP was significantly higher in the COVID-19 positive group than the COVID-19 negative group (MD = 0.40; 95% CI: 0.16 to 0.64, P = 0.001; P < 0.00001 for heterogeneity)." (PMID 36338951, 2022). "Following a MD pattern can result in a favorable profile against COVID-19, as we observed that a higher MD score was associated with shorter length of hospital stay, convalescence, symptoms, as well as reduced severity and inflammatory status (low CRP and ESR levels) in patients with COVID-19." (PMID 35928288, 2022). "Patients with recent COVID-19 had significantly higher neutrophils (P = 0.003) and CRP (P = 0.007) and significantly lower PT (P = 0.033) than patients with non-recent COVID-19." (PMID 36325669, 2022).
COVID-19 (continued). "CRP levels in severe COVID-19 patients were also significantly higher than those in non-COVID-19 (p = 0.029) and non-severe COVID-19 patients (p<0.001)." (PMID 35687545, 2022). "Moreover, serum levels of inflammation-related biomarkers such as SAA, CRP, and ESR were significantly elevated among COVID-19 patients with higher FPG (P < 0.05)." (PMID 35005030, 2022). "Given the negative COVID-19 PCR at the time of presentation as well as normal CRP levels, it was highly unlikely that she had acute COVID-19 pneumonia." (PMID 35186513, 2022). "Leukocytosis, lymphopenia, elevated levels of C-reactive protein (CRP), procalcitonin (PCT), D-dimer, IL-6 (Interleukin-6), Neutrophil to Lymphocyte ratio (NLR), and Lactate dehydrogenase (LDH) have all been observed in COVID-19-infected cancer patients [,7]." (PMID 35127069, 2022). "A combination of laboratory parameters indicative of acute inflammation (CRP), cell death (LDH), and hypercoagulable state (fibrinogen), showed good discrimination value for the development of critical COVID-19 in the derivation cohort, which was higher than any of the parameters alone." (PMID 35407418, 2022). "The clinical characteristics, treatment, laboratory parameters of IL-6, C-reactive protein (CRP), lymphocyte counts before and after TCZ therapy, and clinical outcomes in the 13 patients with COVID-19 were retrospectively evaluated according to the related medical records." (PMID 35308307, 2022). "We not only confirmed the predictive value of high WBC count and neutrophilia for COVID-19 mortality and VS need, but in patients with unfavourable outcomes we also found increased levels of two other markers of inflammation rather than CRP: ferritin and IL-6." (PMID 35584141, 2022). "Additionally, initial and maximum CRP, maximum ferritin, and maximum LDH levels were all significantly (p < 0.05) elevated in COVID-19 patients receiving steroids." (PMID 35893707, 2022). "that enrolled 33 COVID-19 patients revealed negative correlations between the levels of CRP and CD3+, CD3+CD4 +, CD3+ CD8+ subpopulations of lymphocytes, which is consistent with our results." (PMID 35603207, 2022). "Whilst the improvement may be related to better general management of patients with COVID-19, we also noted that patients had lower baseline SCr values and lower inflammatory markers on admission to ICU (i.e. CRP and ferritin)." (PMID 36575315, 2022). "At the same time, there was a negative correlation between adropin levels and CRP, D-dimer, and ferritin levels, which are considered prognostic for COVID-19." (PMID 35703530, 2022). "Finally, we also observed that MMP levels correlate well with laboratory parameters such as CRP, D-Dimer, Ferritin, LDH and Sodium reinforcing the potential contribution of MMPs to pathogenesis of MIS-C and COVID-19." (PMID 36544496, 2022). "Neutrophil-lymphocyte ratio (NLR), C-reactive protein (CRP), interleukin-6 (IL-6), lactate dehydrogenase (LDH), D-dimer, ferritin, and CT thorax were done within 24h of admission before being initiated on any anti-COVID-19 therapy." (PMID 35382199, 2022). "Furthermore, median levels of CRP, GDF-15, IL-6, and sFlt-1 increased with COVID-19 disease severity, whereas the median level of sACE2 decreased with COVID-19 disease severity." (PMID 35453934, 2022). "In long-COVID-19 patients, a 40% drop in HRV followed a 50% rise in CRP." (PMID 36614901, 2022). "Since the beginning of the pandemic, CRP, and IL6 levels have been used as prognostic biomarkers in COVID-19; in addition, IL6 activity has been targeted for treatment by the anti-IL-6 receptor antibody but also to guide treatment and predict response to tocilizumab." (PMID 35783606, 2022). "These parameters when analyzed with non-pregnant reproductive age females in our study results also showed higher neutrophil count and decreased lymphocytes in pregnant females, but CRP was significantly higher in non-pregnant patients infected with COVID-19." (PMID 35371473, 2022).
COVID-19 (continued). "Moreover, C-Reactive Protein, white blood cells (WBC), and HbA1c levels were significantly higher in COVID-19 patients with periodontitis." (PMID 36676965, 2022). "Second, due to the lack of LYMPH and CRP within 24 h of admission in a large number of asymptomatic infection and mild patients with COVID-19, the final sample size of our study was relatively small, and thus the results need to be interpreted with caution." (PMID 36248811, 2022). "On the contrary, COVID-19 patients on standard control therapy showed no reduction in mean CRP levels [WMD = 2.16; 95% CI: -7.59 to 11.92), p-value 0.66; I2 95%]." (PMID 35381033, 2022). "Elevated inflammatory biomarkers like C-reactive protein (CRP) and proinflammatory cytokines like interleukin-2 (IL-2), interleukin-6 (IL-6), interleukin-10 (IL-10), gamma interferon (INF), and tumor necrosis factor-alpha (α-TNF) are higher in severe COVID-19." (PMID 38013720, 2022). "Comparative analysis revealed the superiority of C3a for prediction of COVID-19 progression and mortality over both CRP and D-dimers, while C5b-9 was superior only for prediction of ICU admission over both CRP and D-dimers and for prediction of intubation when compared to D-dimers." (PMID 36143371, 2022). "Contrariwise, we obtained lower values for Htc, VEM, platelets, neutrophils, monocytes, eosinophils, and CRP in the COVID-19 group than the PIMS group, but also without statistical significance." (PMID 36138657, 2022). "Based on this study’s results, taVNS can reduce CRP, IL-6, and depression in patients with COVID-19 but does not interfere in cardiac modulation, COVID-19 clinical symptoms, anxiety, memory, and attention levels." (PMID 36295080, 2022). "We found lower lymphocyte counts and interleukin-1R levels and higher levels of C-reactive protein, interleukin-6, and interleukin-8 in severe compared than in non-severe COVID-19 patients." (PMID 35687545, 2022). "CRP and α-2- microglobulin levels were higher in LTBI/COVID-19 vs. COVID-19." (PMID 36090983, 2022). "Serum levels of inflammation-related biomarkers such as IL-6, C-reactive protein, serum ferritin and coagulation index, and D-dimer were significantly higher in COVID-19 patients with DM compared with those without DM." (PMID 35005030, 2022). "A meta-analysis conducted in 2020 demonstrated that CRP levels were lower in COVID-19 patients with the non-severe disease." (PMID 36585718, 2022). "Likewise, the clinical laboratory parameters ferritin, LDH, CRP, creatinine, AST, urea and d-dimers were increased in COVID-19 patients." (PMID 36557315, 2022). "In the present study, we compared the inflammation markers NP, CRP, and IL-6 in the plasma of COVID-19 and non-COVID-19 patients." (PMID 35529699, 2022). "Recently, more importance has been attached to CRP as one of the very first markers to indicate COVID-19 and its severity, despite CRP being non-specific in nature." (PMID 35453906, 2022). "Both CRP and NLR are markers of systemic inflammation, thus supporting the hypothesis that inflammation has a role in the pathophysiology of delirium in COVID-19 patients." (PMID 35204633, 2022). "Neither IL-1RA nor IL-18 cytokines correlated with CRP when all COVID-19 patients were analysed or when the moderate and severe groups were separated (not shown)." (PMID 35663992, 2022). "Given that no death occurred in the cohorts, we used COVID-19 severity biomarkers including CRP, d-dimer, Alb, and KL-6 as alternatives to mortality to evaluate the clinical efficacy of MP." (PMID 35350784, 2022). "Firstly, children with severe COVID-19 presented early in the course of illness without abnormal biomarkers such as lymphopenia and raised CRP." (PMID 35547549, 2022). "Importantly, as we verified in our group of KTRs with HTN who died, increased levels of CRP, LDH, and D-dimer can be used as prognostic factors in COVID-19." (PMID 36366507, 2022).